NNMT (nicotinamide N-methyltransferase)
Diseases named in the same sentence as NNMT in open-access papers (continued):
Sharing a sentence is not in itself a finding about the gene and the disease.
non-small cell lung carcinoma (5 papers, 2013 to 2024). A group of at least three distinct histological types of lung cancer, including non-small cell squamous cell carcinoma, adenocarcinoma, and large cell carcinoma. "This study aimed to investigate the role of Nicotinamide N-methyltransferase (NNMT) in the drug sensitivity of non-small cell lung cancer (NSCLC) cells, with a focus on its impact on autophagy and resistance to the chemotherapeutic agent osimertinib." (PMID 39035994, 2024).
Parkinson disease (5 papers, 2012 to 2023). A progressive degenerative disorder of the central nervous system characterized by loss of dopamine producing neurons in the substantia nigra and the presence of Lewy bodies in the substantia nigra and locus coeruleus. "High NNMT activity is linked to Parkinson's, cancers, and diseases of affluence." (PMID 22536229, 2012). "Nicotinamide N-methyltransferase (NNMT) is an important metabolic enzyme that is overexpressed in human diseases, including Parkinson’s disease, cardiovascular disease, cancer, and metabolic disorders." (PMID 34895051, 2021). "In this context, it has been suggested in epidemiological studies that the metabolism of nicotinamide, specifically the enzyme nicotinamide N-methyl-transferase (NNMT), could contribute to behavioral and neurodegenerative diseases such as Parkinson’s disease (PD) and schizophrenia." (PMID 30192747, 2018).
bladder urothelial carcinoma (4 papers, 2023 to 2025). "Moreover, two large independent cohort studies have found the presence of CAFs with high expression of nicotinamide adenine dinucleotide (NAD) metabolic enzyme nicotinamide N-methyltransferase (NNMT) to be associated with poor prognosis in urothelial bladder cancer (UBC)." (PMID 40453088, 2025). "Targeting NNMT significantly inhibited tumor growth and enhanced the apoptotic effects induced by anti-PD-L1 antibodies in mouse models of urothelial bladder cancer treated with the NNMT inhibitor 5-amino-1-methylquinoline iodide." (PMID 41226585, 2025). "In contrast, decreased expression of NNMT was found in bladder urothelial carcinoma (BLCA), breast invasive carcinoma (BRCA), cholangiocarcinoma (CHOL), kidney chromophobe (KICH), liver hepatocellular carcinoma (LIHC), lung squamous cell carcinoma (LUSC), and thyroid carcinoma (THCA)." (PMID 36817086, 2023).
endometrial cancer (4 papers, 2019 to 2024). Primary or metastatic malignant neoplasm involving the endometrium (mucous membrane that lines the endometrial cavity). "In regard to endometrial cancer, NNMT expression was significantly higher in primary high-grade and metastatic tumors and NNMT overexpression in metastatic tissue was associated with decreased survival." (PMID 36817086, 2023). "The frequency of NNMT immunoreactivity in tumoral and stromal tissue in endometrial cancer was significantly higher than in benign endometrium (P < 0.001)." (PMID 31652035, 2019). "Stromal expression of nicotinamide N-methyltransferase (NNMT) is correlated with disease progression and metastasis in high grade endometrial cancers (serous and others), in which elevated levels of stromal NNMT in the primary and metastatic tumors are associated with poor overall survival." (PMID 38254014, 2024). "The major limitation of this study was the lack of NNMT immunoreactivity analysis of low-grade endometrial cancer samples." (PMID 31652035, 2019). "NNMT expression has not been previously studied in endometrial cancer (EC)." (PMID 31652035, 2019).
sarcopenia (4 papers, 2024 to 2025). Progressive decline in muscle mass due to aging which results in decreased functional capacity of muscles. "Notably, NNMT has been identified as a potential diagnostic marker and a potential therapeutic target for sarcopenia." (PMID 38838088, 2024). "Among the candidate genes, NNMT was closely associated with muscle aging and upregulated in the muscles of patients with sarcopenia, suggesting its potential value as a diagnostic marker for sarcopenia." (PMID 38838088, 2024). "Nicotinamide N-methyltransferase inhibitors (NNMTis) increase strength and promote the regenerative capacity of aged muscle, thus offering a promising treatment for sarcopenia." (PMID 38969654, 2024). "Among them, the metabolic enzyme nicotinamide N‐methyltransferase (NNMT) was elevated in sarcopenia, and predicted sarcopenia with an area under the curve exceeding 0.7, suggesting it as a potential therapeutic target for sarcopenia." (PMID 38838088, 2024). "Given its involvement in the regulation of these pathways, NNMT emerges as a critical regulator that contributes to the impairment of energy and lipid metabolism in sarcopenia." (PMID 38838088, 2024). "To investigate the role of NNMT in sarcopenia, we established a mouse model of D‐galactose‐induced aging and treated it with low or high concentrations of NNMT inhibitor (NNMTi)." (PMID 38838088, 2024). "Notably, NNMT expression was also significantly upregulated in the sarcopenia group in Dataset_3, with an AUC value of 0.92." (PMID 38838088, 2024). "Notably, NNMT plays a critical role in the metabolic dysregulation of aging skeletal muscles and may serve as a potential biomarker for sarcopenia diagnosis." (PMID 38838088, 2024). "Notably, the metabolic regulator NNMT was also upregulated in patients with sarcopenia." (PMID 38838088, 2024). "However, only the expression level of NNMT was significantly upregulated in the old muscle group compared to the young muscle group, indicating its potential role in the regulation of the age‐related sarcopenia." (PMID 38838088, 2024). "The role of the remaining eight key genes (ALDH1L, EME1, PYGL, NNMT, PHGDH, CD52, CD3D, and ESM1) in COVID-19 and sarcopenia has been less studied, emphasizing their importance in future research." (PMID 38978778, 2024).
thyroid cancer (4 papers, 2023 to 2025). "Another study found that NNMT expression was increased in the thyroid glands of patients with thyroid cancer." (PMID 39807704, 2025).
COVID-19 (3 papers, 2022 to 2024). A disease caused by infection with severe acute respiratory syndrome coronavirus 2. "As CTGF also has a crucial role in the development of lung fibrosis, NNMT-mediated decline in methylation may potentially facilitate the progression of lung fibrosis observed in COVID-19 patients." (PMID 35457123, 2022). "Endogenously caused NAD+ deficiency, common in old age and other predisposing conditions for development of serious COVID-19, most likely stems from elevated NAD+ degradation in NAD+-consuming reactions, coupled with NAD+ salvage pathway stalling, mediated by cooperative activity of NNMT and AOX1." (PMID 35457123, 2022).
Hypertension (3 papers, 2024 to 2025). The presence of chronic increased pressure in the systemic arterial system. "As such, NNMT represents a promising therapeutic target for the prevention and management of hypertension and its associated cardiovascular complications." (PMID 41008588, 2025). "Although there are limited reports regarding the association between NNMT and hypertension, our research has identified a significant association between a SNP in the NNMT gene (rs1941404) and hypertension within the Chinese Han population." (PMID 38919254, 2024). "Thus, influencing Hcy levels may represent another important pathway through which NNMT is implicated in the development of hypertension." (PMID 38919254, 2024). "Taken together, these findings highlight NNMT as a central mediator of hypertension, acting through the NNMT–1-MNA pathway, Hcy accumulation, and NAD+ depletion." (PMID 41008588, 2025). "Another mechanism by which NNMT contributes to hypertension is through NAD+ depletion." (PMID 41008588, 2025). "While direct evidence linking NNMT activity to hypertension is currently lacking, numerous studies have established a strong association between NNMT activity and various metabolic disorders, including cardiovascular diseases." (PMID 38919254, 2024).
kidney cancer (3 papers, 2022). Primary or metastatic malignant neoplasm involving the kidney. "Some clinical studies using the candidate protein survey strategy have reported that NNMT is overexpressed in various tumors, including lung, liver, bladder, colon, and kidney cancers." (PMID 35440542, 2022).
lung adenocarcinoma (3 papers, 2021 to 2026). A carcinoma that arises from the lung and is characterized by the presence of malignant glandular epithelial cells. "The result showed that the protein expression of NNMT in lung adenocarcinoma was significantly higher than those in normal tissues, and the increase in NNMT protein expression level was positively correlated with cancer stage and tumor grade." (PMID 35387964, 2022).
metabolic syndrome (3 papers, 2020 to 2025). A cluster of metabolic risk factors for CARDIOVASCULAR DISEASES and TYPE 2 DIABETES MELLITUS. "Emerging evidence suggests that nicotinamide N-methyltransferase (NNMT), an enzyme that catalyzes the methylation of nicotinamide, may play a role in the pathophysiology of T2DM and metabolic syndrome." (PMID 40724965, 2025).
metastatic tumors (3 papers, 2019 to 2024). "NNMT immunoreactivity was seen in 52.4%, 65.4%, 90%, and 90% of patients within the endometrial tumor, stroma adjacent to the tumor, omental metastatic tumor, and stroma adjacent to the metastatic omental tumor, respectively." (PMID 31652035, 2019). "The frequency of NNMT immunoreactivity was significantly higher in metastatic tumors compared to the primary tumors (P = 0.002)." (PMID 31652035, 2019). "Of note, NNMT expression was significantly higher in the stroma adjacent to the metastatic tumor than the stroma adjacent to the primary tumor (P = 0.003)." (PMID 31652035, 2019).
osteoporosis (3 papers, 2021 to 2024). A condition of reduced bone mass, with decreased cortical thickness and a decrease in the number and size of the trabeculae of cancellous bone (but normal chemical composition), resulting in increased fracture incidence. "By intersecting the target miRNAs of HOTAIR, the target miRNAs of NNMT, and the DE-miRNAs of GSE91033, we identified miR-378g as a potential miRNA that linked HOTAIR and NNMT in osteoporosis." (PMID 34895051, 2021). "In osteoporosis, both miR-29b-3p and miR-378g regulate osteogenic differentiation of BMSCs by targeting NNMT." (PMID 38919254, 2024). "In future, we will establish a model of osteoporosis with ovariectomized rats, to study the effect of XIST/miR-29b-3p/NNMT signal axis on OP." (PMID 34486487, 2021).
osteosarcoma (3 papers, 2021 to 2025). A usually aggressive malignant bone-forming mesenchymal neoplasm, predominantly affecting adolescents and young adults. "Results reported in our recent published works showed high NNMT expression levels in association with Merkel cell carcinoma (MCC) and osteosarcoma (OS)." (PMID 41301471, 2025). "Our recent data demonstrated that NNMT upregulation in osteosarcoma (OS) and Merkel cell carcinoma (MCC) led to a significant increase in cell proliferation and migration ability, together with a reduction in sensitivity to chemotherapeutic treatment." (PMID 41301471, 2025). "However, recent studies have highlighted the critical role of NNMT in osteosarcoma progression, demonstrating that its upregulation contributes to increased tumor aggressiveness and resistance to therapy." (PMID 40332124, 2025). "In addition, nicotinamide N-methyltransferase (NNMT), another methyltransferase previously implicated in different metabolic disorders and cancer development, has also been associated to the acquisition of a stemness state in osteosarcoma." (PMID 34198693, 2021).
pulmonary hypertension (3 papers, 2016 to 2025). Increased pressure within the pulmonary circulation due to lung or heart disorder. "In the present work, we demonstrated, to our knowledge for the first time that pulmonary hypertension is associated with the activation of the NNMT-MNA pathway in rats and in humans." (PMID 27581040, 2016).
serous carcinoma (3 papers, 2022 to 2025). "In addition, it has been reported that NNMT has been overexpressed in the stroma of advanced high-grade serous carcinoma and may contribute to decreased survival." (PMID 40853419, 2025). "Indeed, stromal nicotinamide N-methyltransferase (NNMT) is necessary and sufficient for CAF function (i.e., expression of CAF biomarkers, cytokine secretion, deposition of an oncogenic ECM) in high-grade serous carcinoma." (PMID 35267539, 2022).
skin cancer (3 papers, 2021 to 2023). "Several studies have explored the role of NNMT in skin cancer: a significantly higher NNMT expression was observed in cutaneous melanoma and BCC specimens." (PMID 38201930, 2023). "NNMT is broadly explored in cancer, and it was found to be upregulated in skin cancer." (PMID 38201930, 2023). "Overexpression of NNMT was also exhibited in AK, even higher than cutaneous SCC; for a review on the role of NNMT in skin cancer, see the stimulating paper by Campagna and coworkers." (PMID 38201930, 2023). "Among these promising biomarkers, nicotinamide N-methyltransferase (NNMT) has emerged as a key player in various malignancies, including skin cancer." (PMID 37629523, 2023).
Alzheimer disease (2 papers, 2021 to 2024). A progressive, neurodegenerative disease characterized by loss of function and death of nerve cells in several areas of the brain leading to loss of cognitive function such as memory and language. "NNMT upregulation is related to many diseases, including PD, Alzheimer’s disease, and many cancers." (PMID 38399441, 2024).
chronic obstructive pulmonary disease (2 papers, 2013 to 2021). A chronic and progressive lung disorder characterized by the loss of elasticity of the bronchial tree and the air sacs, destruction of the air sacs wall, thickening of the bronchial wall, and mucous accumulation in the bronchial tree. "A number of studies have shown that NNMT expression is increased as a survival response to disease pathogenesis in diverse diseases including inflammation, cirrhosis, hepatitis, thrombosis and chronic obstructive pulmonary disease." (PMID 33387303, 2021).
colon adenocarcinoma (2 papers, 2023). "More notably, 9 out of 33 cancer types displayed a strong relationship between NNMT and methyltransferases with unknown substrates, with very strong relationships evident in LUSC and stomach and colon adenocarcinomas (STAD and COAD)." (PMID 37883365, 2023).
folate deficiency (2 papers, 2023 to 2025). A nutritional condition produced by a deficiency of FOLIC ACID in the diet. "However, only when together with the NNMT GG genotype and other confounding factors, such as age, folate deficiency, and/or MTHFR C677T, were they associated with an elevation of plasma homocysteine." (PMID 37273715, 2023).
gynecologic cancers (2 papers, 2017 to 2024). "Previous studies, including those on gynecologic cancers, have demonstrated a significant correlation between NNMT overexpression and advanced disease stage, indicating an association between NNMT overexpression and cancer progression, invasion, and metastasis." (PMID 39295619, 2024). "Specifically, carcinomas of ovary, cervix, vulva and vagina, all showed significantly upregulated NNMT expression compared to healthy tissues." (PMID 28412735, 2017).
head and neck squamous cell carcinoma (2 papers, 2023 to 2025). A squamous cell carcinoma that arises from any of the following anatomic sites: lip and oral cavity, nasal cavity, paranasal sinuses, pharynx, larynx, and salivary glands. "Biomarkers such as HPV DNA/mRNA, HPV-E6, EBV RNA, p16^Ink4a, and the more recently identified NNMT and PON2 play critical roles in the diagnosis, prognosis, and prediction of treatment response in head and neck squamous cell carcinoma (HNSCC)." (PMID 40864763, 2025).
non-alcoholic steatohepatitis (2 papers, 2020). "Previous reports described that an A allele and mutated AA genotype of the rs694539 NNMT gene were associated with non-alcoholic steatohepatitis and the stage of non-alcoholic fatty liver disease." (PMID 32651404, 2020).
ovarian serous carcinoma (2 papers, 2020 to 2025). "In high-grade serous ovarian carcinoma, NNMT expression in the tumor stroma is involved in the differentiation of cancer-associated fibroblasts, suggesting a potential role in cancer progression in the stroma." (PMID 40853419, 2025). "Prolonged glucose deprivation has been shown to contribute to the phenotypic plasticity of ovarian serous carcinoma cells (OSCS), characterized by acquiring stem cell properties and resistance to glucose restriction, dependent on the expression of nicotinamide N-methyltransferase (NNMT)." (PMID 33182817, 2020).
ovarian tumors (2 papers, 2021 to 2024). "The decreased ATP levels from BRCA1 depletion are mainly due to NNMT upregulation, making NNMT a potential therapeutic target in BRCA1-deficient ovarian tumors." (PMID 39272943, 2024). "Interestingly, a recent proteomic analysis of ovarian tumors reported that the metastatic stromal proteome was notably uniform and characterized by the overexpression of the nicotinamide N-methyltransferase (NNMT) as well as several proteins regulated by it." (PMID 34359678, 2021). "Notably, the overexpression of stromal NNMT in ovarian tumors led to the depletion of SAM concomitantly with DNA and histone hypomethylation, which were in turn associated with widespread gene expression alterations." (PMID 34359678, 2021).
schizophrenia (2 papers, 2018 to 2021). A major psychotic disorder characterized by abnormalities in the perception or expression of reality. "In summary, we provide fundamental insights into neuronal NNMT/ANMT-1 as pivotal regulator of behavior, neurodegeneration, and lifespan by controlling neuronal autophagy, potentially influencing PD and schizophrenia risk in humans." (PMID 30192747, 2018). "A potential role in both PD and schizophrenia is attributed to the enzyme nicotinamide-N-methyltransferase (NNMT), which is expressed in all body tissues including the nervous system and represents a key player in NAD+/NADH metabolism." (PMID 30192747, 2018). "We have detailed this novel molecular mechanism regulating neuronal autophagy during aging and raise the possibility of the NNMT pathway as a potential target for neuroprotective interventions in PD, schizophrenia, and other neurological diseases." (PMID 30192747, 2018). "Although this study did not examine NNMT protein or activity levels, the authors suggested that NNMT is involved in the aetiology of schizophrenia via its regulation of cellular homocysteine concentrations, which are increased in the plasma of schizophrenia patients." (PMID 33387303, 2021).
adenoma (1 paper, 2020). A neoplasm arising from the epithelium. "The results showed that stromal NNMT expression in CRC tissues and CRC liver metastases were significantly higher as compared with normal, paracarcinoma and adenoma tissues (P < .01)." (PMID 31989785, 2020).
alopecia (1 paper, 2022). Hair loss usually from the scalp. "Our findings suggest that NNMT and QPRT, which link NAD + expression and activity, may be deemed potential therapeutic targets for alopecia treatment." (PMID 35181715, 2022).
asthma (1 paper, 2022). "In this study, four hub genes including HIF1A, OCRL, NNMT, and PER1 were identified as potential markers associated with asthma metabolism by bioinformatics analysis." (PMID 36676950, 2022). "Through machine learning and bioinformatics techniques, four hub genes, including HIF1A, NNMT, OCRL, and PER1, were identified as potential markers associated with asthma metabolism, especially HIF-1A." (PMID 36676950, 2022). "In the present study, we merged the differentially expressed genes (DEGs) of asthma in the GEO database with the metabolic genes obtained by Genecard for bioinformatics analysis and successfully screened out the metabolism-related hub genes (HIF1A, OCRL, NNMT, and PER1)." (PMID 36676950, 2022).